C18orf63 (chromosome 18 open reading frame 63)
Synonyms: DKFZP781G0119
Tractability: No criterion of Open Targets' tractability assessment is met for any kind of drug.
Gene: Protein-coding gene on chromosome 18 (74,315,839 to 74,359,189, forward strand). Ensembl gene ENSG00000206043.
Subcellular location (Human Protein Atlas): Mitochondria
Gene Ontology:
Biological process: male gonad development
Genetic constraint (gnomAD): Loss-of-function variants: 17 observed, 25.94 expected, observed/expected ratio (o/e) 0.66, 90% interval 0.45 to 0.98. The upper end of that interval is the gene's LOEUF score, 0.98, which puts it in group 4 of 6, group 1 being the genes least tolerant of losing a copy. Missense variants: 390 observed, 402.39 expected, observed/expected ratio (o/e) 0.97, 90% interval 0.89 to 1.05. Synonymous variants: 124 observed, 148.31 expected, observed/expected ratio (o/e) 0.84, 90% interval 0.72 to 0.97.
Homologues: Orthologues: chimpanzee C18H18orf63 (98% identical), macaque C18H18orf63 (94% identical), pig C18orf63 (72% identical), dog C18orf63 (71% identical), rabbit C18orf63 (69% identical), mouse Gm17266 (62% identical), rat C18h18orf63 (61% identical), Caenorhabditis elegans F21F3.4 (11% identical).
Diseases named in the same sentence as C18orf63 in open-access papers:
C18orf63 is named in the same sentence as 2 diseases in open-access papers, as found by Europe PMC text mining. Sharing a sentence is not in itself a finding about the gene and the disease. The quoted sentences say what the papers report.
alcoholic cirrhosis (1 paper, 2024). "Further UMAP analysis indicated that the expression levels of genes such as PRDM16 and WWTR1 were elevated in alcoholic cirrhosis patients, while other genes like C18orf63 and RNU6ATAC39P showed decreased expression." (PMID 39588518, 2024).
lung adenocarcinoma (1 paper, 2026). A carcinoma that arises from the lung and is characterized by the presence of malignant glandular epithelial cells. "The transcriptomic data revealed that five genes (CAMK1D, BCAS3, DNAH1, PDE10A, and C18orf63) were differentially expressed between lung adenocarcinoma patients and healthy individuals." (PMID 41868793, 2026).